SMAD4 (SMAD family member 4)
Diseases named in the same sentence as SMAD4 in open-access papers (continued):
Sharing a sentence is not in itself a finding about the gene and the disease.
pancreatic cancer (continued). "Such SMAD4 mutations could trigger the hyperactivation of the TGF-β signaling pathway 21, indicating the vital role of this pathway in pancreatic cancer progression." (PMID 35637952, 2022). "It promotes pancreatic cancer stemness in Smad4-dependent or independent manners." (PMID 33537082, 2021). "Therefore, it can be understood that the inactivation of Smad4 in pancreatic cancer cells removes p27 protein from the equation contributing to the disabling of G1/S checkpoint." (PMID 38107772, 2021). "Immunohistochemistry, such as SMAD4, MUC5AC, and CDX2 expression, may be useful to distinguish them; SMAD4 nuclear expression is more preserved in iCCA compared with pancreatic cancer." (PMID 34201284, 2021). "Authors of one study hypothesized that after Smad4 was silenced in human pancreatic tumor cells, Smad4 was still needed for TGF-β-induced cell cycle arrest and migration; however, Smad4 was not involved in TGF-β-induced EMT." (PMID 34383767, 2021). "The role of SMAD4 in CRC is similar to that in pancreatic cancer." (PMID 34301194, 2021). "Moreover, ZNF185 contributes to chemotherapy resistance, in combination with elevated SMAD4 expression, in pancreatic cancer." (PMID 34421347, 2021). "In addition, Smad4 represents a barrier in Kras-mediated malignant transformation in a pancreatic cancer model." (PMID 34381046, 2021). "SMAD4 loss was associated with shorter OS (18.3 months versus 30.1 months for preserved SMAD4; p < 0.001) and disease-free survival (DFS) (6.0 months versus 13.5 months for preserved SMAD4; p < 0.001) in patients with resectable pancreatic cancer." (PMID 32429474, 2020). "The reintroduction of SMAD4 was confirmed by western blot using Panc-1, a pancreatic cancer cell line with no mutation or loss of the SMAD4 genetic locus, as a control reference." (PMID 32420409, 2020). "Besides, studies have shown that TRIM33 can participate in the TGF-β signaling pathway by binding to phosphorylated SMAD2/3 or monoubiquitinated SMAD4 in hepatocellular carcinoma, human chronic myelomonocytic leukemia, and pancreatic cancer." (PMID 32908919, 2020). "HEATR1, ZNF185, and SMAD4 could affect the chemosensitivity of gemcitabine and may be the indicators of gemcitabine selection in the chemotherapy of pancreatic cancer." (PMID 32565799, 2020). "Overall, our findings suggest that for tumours of the two major pancreatic cancer subtypes, oncogenesis may be primarily driven by perturbation in either SMAD4 or mTOR signalling." (PMID 31988390, 2020). "Given that SMAD4 is an identified miR-301a target in multiple cancers, including lung, prostate, and pancreatic cancers, the present study investigated whether SMAD4 was upregulated in fibroblasts with miR-301a inhibition." (PMID 32585629, 2020). "Several lines of evidence showed that Smad4 may act as a tumor suppressor in colorectal cancer and pancreatic cancer." (PMID 31721429, 2020). "In advanced pancreatic cancers treated by gemcitabine, SMAD4 loss had no impact on OS (HR 1.008; p = 0.656) but was associated with a prolonged PFS (HR 1.565, p = 0.038)." (PMID 32429474, 2020).
pancreatic cancer (continued). "Moreover, we also preliminarily discovered that knocking down ZNF185 served as increasing the chemosensitivity via SMAD4 in pancreatic cancer which was confirmed by in vitro and in vivo analysis." (PMID 32565799, 2020). "SMAD4 depletion also induces radioresistance in pancreatic cancer both in vitro and in vivo." (PMID 32651227, 2020). "Therefore, we undertook further analyses to determine the effect of SMAD4 Y353C located in the MH2 region on pancreatic cancer cells and revealed its important role among 4 novel heterozygous missense mutations." (PMID 31684910, 2019). "Smad4, also known as deleted in pancreatic cancer 4 (DPC4), is commonly inactivated in PDAC." (PMID 30832219, 2019). "Besides, HIF-2α transcribes and maintains the levels of β-catenin and Smad4 in pancreatic tumors cells." (PMID 31480221, 2019). "SMAD4 is a tumor suppressor gene that is inactivated in 50–55% of pancreatic cancer patients." (PMID 31377855, 2019). "In addition to the classical TGF-β/SMAD4 signalling pathway, other pathways are also closely related to ectopic SMAD4 in the development of pancreatic carcinoma." (PMID 31684910, 2019). "Smad4 (also termed deleted in pancreatic carcinoma, locus 4 [DPC4]), was initially identified as a candidate tumor suppressor gene whose inactivation may play a role in pancreatic cancer." (PMID 31349837, 2019). "In addition, SMAD4 silencing in pancreatic tumor cells and keratinocytes has been shown to abolish TGFβ induced migration, therefore highlighting a vital role for SMAD4 in microglial migration." (PMID 29861845, 2018). "Further, in pancreatic tumours displaying either SMAD4 deletions or SMAD4 under-expression, ligand stimulation of the TGF-β pathways activates non-canonical pathways including the MAPK, p38/JNK, and PI3K-mTOR pathways which can function independently of SMAD signalling." (PMID 30018740, 2018). "Although stratification of patients based on Smad4 (dpc4) is included in the currently recruiting Radiation Therapy Oncology Group (RTOG) 1201 study, the diagnosis of pancreatic cancer is often made on scant biopsy material or cytology, which limits the accuracy of SMAD4 immunohistochemistry." (PMID 28190636, 2017). "The signalling cascade through the complex Smad2/3/4 may be very important in some type of pancreatic cancer cells as Smad4 is a critical mediator of TGFβ signalling." (PMID 29064388, 2017). "Furthermore, 60% of pancreatic cancer is observed to lost 18q21 chromosome that harbors the Smad4 gene." (PMID 28794854, 2017). "The tumor suppressor mothers against decapentaplegic homolog 4 (SMAD4) (also known as deleted in pancreatic cancer 4 (DPC4)) was first described in 1996 by Hahn and co-workers and is thought to regulate pancreatic cell proliferation and apoptosis via the transforming growth factor-β (TGF-β) pathway." (PMID 28534865, 2017). "Indeed, pancreatic cancer progression requires shutting down the tumor-suppressive effects of TGF-β signaling through mutation Smad transcription factors (Smad2, Smad4)." (PMID 28794854, 2017). "Smad4 loss alone did not initiate human pancreatic cancer formation since conditional deletion of Smad4 was not sufficient to induce either pancreatic intraepithelial lesions or invasive cancer, emphasizing the importance of multiple genetic hits." (PMID 28067794, 2017).
pancreatic cancer (continued). "Encouraging results have been reported by recent studies showing that pancreatic carcinoma could be inhibited by controlling several biomarkers such as SMAD4, CXCR2, ABCG2 and Kras." (PMID 28077929, 2017). "Through negative regulation of SMAD4, miR-301a promotes pancreatic cancer progression." (PMID 27230112, 2016). "We investigated whether chronic exposure to EGF modifies in a SMAD4-dependent manner pancreatic cancer cell signalling, proliferation and invasion in response to EGF, TGFβ1 and S100A8/A9." (PMID 27655713, 2016). "SMAD4 was previously shown to be involved in pancreatic cancer tumorigenesis." (PMID 26053092, 2015). "High TGF-β1 plasma level, SMAD4 SNP or TGF-βR2/SMAD4 tumor protein expression may suggest a dependence on this pathway in patients with advanced pancreatic cancer." (PMID 24465802, 2014). "The present study therefore investigated whether the Smad4 gene is actually present in BxPC3 cells, a pancreatic cancer cell line widely used to represent a Smad4-null genotype." (PMID 24944686, 2014). "In total, 30% of pancreatic cancers harbor a homozygous deletion of Smad4." (PMID 24944686, 2014). "Higher frequency of KRAS, P16 and SMAD4 mutations in extrahepatic CCA suggest a molecular phenotype that resembles pancreatic cancer rather than intrahepatic CCA." (PMID 25536104, 2014). "Transforming growth factor, beta (TGFB) signal is considered to be a tumor suppressive pathway based on the frequent genomic deletion of the SMAD4 gene in pancreatic cancer (PC); however; the role of the activin signal, which also belongs to the TGFB superfamily, remains largely unclear." (PMID 24886203, 2014). "Smad4 was originally identified as a tumor suppressor gene in pancreatic carcinomas." (PMID 24636138, 2014). "As a negative regulator of Smad4, SnoN may also play a role in the development of pancreatic cancer." (PMID 23418461, 2013). "However, SMAD4 gene mutation was uncommon in HNSCC in comparison with 35% point mutation rate in pancreatic cancer and 12% in colon cancer." (PMID 23826135, 2013). "Ron is highly expressed in Smad4 mutant pancreatic cancer cells." (PMID 23922886, 2013). "Moreover, the results of univariate Cox proportional hazards analysis for the cytoplasmic expression of RhoT1, Smad4 and p16 in pancreatic cancer tissues showed that the low-expression of RhoT1 was correlated with an increase in the risk of death (P = 0.042)." (PMID 22860091, 2012). "Furthermore, low cytoplasmic expressions of RhoT1 and Smad4 were associated with LNM and worse survival in patients with pancreatic cancer." (PMID 22860091, 2012). "However, the significance of p16 and Smad4 inactivation for complex and tissue-specific aspects of pancreatic cancer progression, such as angiogenesis and metastasis, is less understood." (PMID 22860091, 2012). "In addition, TGF-β signals through SMAD4, a critical tumor suppressor inactivated in half of pancreatic cancers." (PMID 23326260, 2012). "The tumor suppressor Smad4, also known as dpc4 (deleted in pancreatic cancer), is particularly affected by these genetic alterations, being mutated or deleted in no less than half of human pancreatic cancer, where it was originally characterized." (PMID 27340590, 2012).
pancreatic cancer (continued). "Studies have shown SMAD4 gene to be inactivated in 55% of pancreatic cancers." (PMID 22195733, 2011). "In addition to pancreatic cancer, SMAD4 is somatically inactivated in colon and biliary cancers, gastric cancer, homozygous deletions of SMAD4 have been detected in a small percentage of invasive ductal carcinomas." (PMID 21835029, 2011). "TGF-β1 induces drug resistance in a Smad4-null pancreatic cancer cell line." (PMID 20684793, 2010). "This is particularly important in pancreatic cancer chemotherapy because more than 50% of pancreatic cancers have inactivated Smad4 protein, which may result in activation of the Smad4-independent TGF-β1 pathway when patients undergo such treatment." (PMID 20684793, 2010). "TNFα can stimulate EMT and motility in pancreatic carcinoma cells, even if these lack SMAD4." (PMID 24281218, 2010). "This study suggests that TIF1γ is critical for tumor suppression in the pancreas, brings new insight into the genetics of pancreatic cancer, and constitutes a promising model to decipher the respective roles of SMAD4 and TIF1γ in the multifaceted functions of TGFβ in carcinogenesis and development." (PMID 19629168, 2009). "Smad4 increased basal and/or TGFβ-induced expression of LM-332 in Smad4-reexpressing colon and pancreatic cancer cells leading to a huge increase in the extracellular release of the heterotrimer and to the deposition in BM-like structures at contact sites with fibroblasts." (PMID 18664273, 2008). "This might be expected to abolish TGF-β signaling, however, recent studies have clearly demonstrated Smad-4 independent signaling pathways in pancreatic cancer cells as well as in several other systems." (PMID 18157915, 2007). "SMAD4, CK 19 and CA 19-9 in pancreatic tumor cell immunoreactivity is highlighted in this table." (PMID 17587453, 2007). "The SMAD4(DPC4) gene was recently identified as a candidate pancreatic cancer suppressor gene." (PMID 10993648, 2000). "Notably, SMAD4 - a tumor suppressor gene frequently deleted in pancreatic cancer - may form a feedback loop with BMP4 regulation." (PMID 40837015, 2025). "In addition, deletion of SMAD4 gene produced protective effects against pancreatic cancer." (PMID 36912230, 2023). "Therefore, we were interested in whether knocking out SMAD4 in the PANC-1 cell line, which has been found to be associated with a worse prognosis in pancreatic carcinoma, would affect resistance to MTO." (PMID 37049199, 2023). "Hence, while SMAD4 may have a modest inhibitory effect on PD-L1 in tumor cells, SMAD4 indirectly promotes PD-L1 expression in the pancreatic tumor microenvironment by enhancing T-cell infiltration and IFNγ biosynthesis." (PMID 35155243, 2022). "Furthermore, we downloaded the public data (TCGA-PAAD project) of pancreatic cancer patients from TCGA including clinical information on gemcitabine treatment and SMAD4 expression datasets to determine if SMAD4 expression in a PDAC patient is clinically correlated with gemcitabine response." (PMID 36127339, 2022).
pancreatic cancer (continued). "For instance, there were findings suggest that the loss of Smad4 and PTEN may lead to more aggressive disease and poor prognosis in patients with colorectal adenocarcinoma compared to the loss of SMAD4 or PTEN alone, pancreatic cancer, lung cancer, and invasive intestinal-type gastric cancer." (PMID 33825073, 2021). "The loss of SMAD4 will abrogate the canonical TGF-β/SMAD4 signaling pathway, and it may make pancreatic cancer more aggressive." (PMID 34880877, 2021). "Besides, the relevance of our study was confirmed in the samples of pancreatic cancer patients, and we demonstrated that HEATR1, ZNF185, and SMAD4 expression are significantly associated with the prognosis with pancreatic cancer in the patients treated with gemcitabine chemotherapy." (PMID 32565799, 2020). "Importantly, the expressions of BRCA2 and Smad4 genes were up-regulated after challenge, which suggested the infection might also inhibit the developing of pancreatic cancer of host." (PMID 30792708, 2019). "In this study, both SMAD4-deleted pancreatic cancer cell lines and patient-derived organoids exhibited higher sensitivity toward gemcitabine, supporting the use of SMAD4 gene copy number variation as a therapeutic biomarker for treating pancreatic cancer patients." (PMID 31569425, 2019). "A meta-analysis of 4247 patients in 20 published articles concluded that the immunohistochemical loss of SMAD4 predicted a poor overall survival in both Asian and Caucasian patients with pancreatic cancer, but did not correlate with tumor size, differentiation, or lymph node metastasis." (PMID 28067794, 2017). "If the combination of RUNX3 and SMAD4 status could predict the behavior of PDAC, analyzing RUNX3 and SMAD4 protein expression status by immunohistochemistry in resected or biopsied PDAC tissues would greatly benefit pancreatic cancer patients by helping to guide treatment plans." (PMID 29100342, 2017). "Although inactivation or loss of Smad4 occurs in the majority of pancreatic cancer, targeting Smad4 or other Smads as treatment of PDAC may not be successful due to presence of the Smad-independent TGF-β signaling pathway." (PMID 28067794, 2017). "Additionally, loss of Smad4 staining was a significant prognostic marker for a poor outcome in different cancers (cervical carcinoma, colorectal cancer, gastric cancer and pancreatic cancer), regardless of the number of participants (small or large)." (PMID 25333693, 2014). "However, the actual role of SMAD4 in pancreatic cancer is still regarded as controversial." (PMID 24465802, 2014). "In pancreatic cancer, there is an imbalance between the canonical Smad transduction which is debilitated due to Smad4 mutations and the noncanonical MAPK pathway which, in addition to the nonaffected transduction from TGFβ receptors, receives the input from the activated K-ras." (PMID 23049538, 2012). "Therefore, we propose that a Smad4-independent TGF-β1 pathway may promote the drug resistant phenotype in pancreatic cancer through PKCα and P-gp." (PMID 20684793, 2010). "In addition, the inactivation of down-stream targets of TGF-β induced signalling pathways, such as Smad4 which is mutated or deleted in a high percentage of pancreatic cancers, may lead to a subsequent induction of TGF-β1 expression in pancreatic cancers." (PMID 11870516, 2002).